TNF (tumor necrosis factor)
Diseases named in the same sentence as TNF in open-access papers (continued):
Sharing a sentence is not in itself a finding about the gene and the disease.
kidney disease (continued). "The degree of macrophage infiltration into the kidney is a major parameter used to predict the progression of renal disease, and activated macrophages express several inflammatory mediators, including TNF-α and IL-6, which play important roles in the pathogenesis of cisplatin-induced renal injury." (PMID 23476708, 2013). "A future study should evaluate whether TNF-α and its soluble receptors predict the longitudinal progression of kidney disease." (PMID 18681974, 2008). "Since TNF-based therapeutics are already approved for human use, and several more are likely to be found in the future based on TNFSF ligands, the findings of our study recommend validating results of rodent studies, not only kidney diseases but also other pathogenic disorders, in human studies." (PMID 28927419, 2017). "Previous studies suggest that specifically targeted therapeutics that focus on inhibiting individual TNFR1 or TNFR2, may help balance the proinflammatory and immunomodulatory functions of TNF in renal disease and thus represent potential therapeutics with a better clinical outcome." (PMID 29340080, 2017). "Several reviews have highlighted its effects on renal inflammation and fibrosis, elucidating its impact on inflammatory factors such as TNF-α, IL-1β, IL-6, and the TGF-β-Smad pathway, which contribute to fibrosis during kidney disease progression." (PMID 40442892, 2025). "TNF-α binds to the TNF receptor, activating NF-κB and controlling various inflammatory genes that are vital in kidney disease." (PMID 38804362, 2024). "Secretion of TNF, CSF2, MMP9, CTGF and PAI-1 were measured, as these molecules are known to modulate kidney disease progression in various animal models of CKD." (PMID 39005931, 2024). "In animal models of renal diseases, treatment with H2S donors could restore H2S levels and improve renal functions by preventing oxidative stress, inflammation, and necrosis by reducing superoxide formation, lipid peroxidation, iNOS, NF-κB, TNF-α, and malondialdehyde levels." (PMID 36829595, 2023). "In conclusion, the present results indicate that IS may contribute to kidney disease by accelerating senescence, through the regulation of senescence markers and by modulating inflammatory and profibrotic processes, as evidenced by changes in the TNF-α/NF-ĸB pathway and the EMT process." (PMID 37104179, 2023). "Considering the relevance of the TNF signaling pathways in CKD pathophysiology, studies on the efficacy of the existing TNF biologics in renal diseases would be useful." (PMID 35328704, 2022). "It has been determined that pro-inflammatory cytokines and chemokines such as TNF-α, IL-1β, IL-6, IL-8, and MCP-1 are involved in the development of kidney diseases." (PMID 32028746, 2020). "The elevation of pro-inflammatory cytokines such as IL-1β, IL-6 and TNF-α is common in CKD (Furuichi, Kaneko & Wada, 2009) and has been used as a predictor of mortality in patients with kidney disease." (PMID 31275747, 2019). "In addition, it has been shown that the serum concentrations and urinary excretion of TNF-α are increased in patients with various kidney diseases, suggesting that excessive TNF-α in the systemic circulation may result in the upregulation of MCP1 in the kidney." (PMID 31295940, 2019). "Similar to TNF-α, TGF-β1, which is a potent pro-fibrotic and pro-apoptotic cytokine, was proved to be involved in renal disease." (PMID 30641998, 2019). "TNF-α: tumor necrosis factor alpha; IL-6: interleukin 6; CRP: ultra-sensitive C-reactive protein; Hcy: homocysteine; KDQOL-SF 36: kidney disease quality of life short form 36 questionnaire." (PMID 29694512, 2018). "In active renal disease patients, the IL-1β levels were positively correlated with SLEDAI score (r = 0.33, P < 0.001) compared with TNF-α (r = 0.18, P = 0.001) and IL-6 (r = 0.11, P = 0.01)." (PMID 25548434, 2014).
kidney disease (continued). "In proteinuric kidney diseases, excess exposure of proximal tubular cells to albumin, FFA bound to albumin or cytokines such as TNFα is detrimental." (PMID 21966476, 2011). "Elevated TNFR levels are strong predictors of macroalbuminuria and kidney disease progression in both T1DM and T2DM, suggesting that urinary TNF-α and circulating TNFR levels may serve as biomarkers for DKD progression." (PMID 39941397, 2025). "Brugos and coworkers found that interleukin-1 (IL-1) and tumor necrosis factor-α (TNF-α) were elevated significantly in the urine of patients without renal disease, while interferon-γ (IFN-γ) was elevated in the urine of LN patients." (PMID 35913213, 2022). "The expression of the pro-inflammatory cytokines TNF-α and IL-6 was similar between patients with and without DM in the early stages of kidney disease." (PMID 36232497, 2022). "Moreover, oxidized albumin in kidney disease patients is independently correlated with higher plasma levels of transforming growth factor beta (TGF-β1), tumor necrosis factor (TNF-α), and interleukin (IL)-1β and IL-6." (PMID 33800425, 2021). "Interestingly, low doses of TNF-α, when administered exclusively at late disease stages to NZB/W F1 mice, accelerated renal disease." (PMID 33572870, 2021). "Usually, TNF-α is recognized to worsen inflammation and TEC injury in kidney diseases." (PMID 33428678, 2021). "Serum and urinary levels of TNF are increased in patients with DN when compared with nondiabetic individuals or with diabetic subjects without renal disease." (PMID 32046074, 2020). "The activation of growth factors such as transforming growth factor-β (TGFB) and inflammatory cytokines leads to the activation of tumor necrosis factor-α (TNFA) signals and promotes cell repair and remodeling, thereby further aggravating kidney disease and fibrosis." (PMID 32656264, 2020). "In addition, our experiments show that CaD prevents the increase and upregulation/activation of several pro-inflammatory cytokines (IL-6, CXCL1, IL-1ß, TNF-α, and MCP-1) that play a significant role in renal-disease progression." (PMID 31935212, 2020). "In addition, levels of IL-1α, IL-1β TNFα, INFγ, IL-2 and IL-10 were elevated in the sera of CKD compared to sham, suggesting that the chronic state of renal disease affects the inflammatory network." (PMID 29889834, 2018). "Anti-TNF therapy was stopped after 6, 6.5, and 9 years due to stable renal disease without proteinuria." (PMID 28834898, 2017). "Elegant studies from the Fernandes laboratory have related the delayed onset and decreased severity of renal disease exhibited in fish oil-fed NZBWF1 mice to reduced IL-1β, TNF-α, TGFβ1, ICAM-1 and fibronectin expression and increased expression of antioxidant enzymes." (PMID 27513935, 2016). "However, during a late stage of kidney disease, injured proximal tubule cells can enter a profibrotic, pro-inflammatory status via the expression of CCL2 and the activation of the NF-κB, TNF-, and AP-1 signaling pathways, thus likely serving as contributors to CKD progression." (PMID 40723524, 2025). "Interestingly, it has been demonstrated that various pro-inflammatory cytokines, including tumor necrosis factor-α (TNF-α), Interleukin-2 (IL-2), and transforming growth factor-β1 (TGF-β1), could induce endothelial cells into myofibroblasts in renal diseases." (PMID 37288756, 2023). "For renal disease, despite the fact that the exact mechanism has not been identified yet, the mutual inflammatory cytokines (CRP, IL-1, IL-6 and TNF-α) can invade renal tissue causing interstitial fibrosis, tubular injury and infiltration of different inflammatory cells." (PMID 37957565, 2023). "Although we did not measure these cytokines (e.g., IL-1β and TNF-α), it was proposed that those cytokines concomitant with elevated serum ferritin might be considered to contribute to kidney disease progression." (PMID 37880328, 2023).
kidney disease (continued). "However, the role of TNF-α and its receptors in renal diseases is not completely clarified." (PMID 35328704, 2022). "However, data about the effect of anti-TNF in AS patients without kidney disease is lacking." (PMID 35962246, 2022).
neurological diseases (184 papers, 2008 to 2026). "TNFRSF1A gene encodes TNFR1, a major mediator of TNF-α signaling, crucial in inflammation, apoptosis, and immune response, and is linked to various disorders, especially autoinflammatory and neurological diseases." (PMID 40520613, 2025). "This de novo synthesis of TNF-α represents a significant facet of the neuroinflammatory response linked with various neurological disorders (Olmos and Lladó 2014)." (PMID 39374132, 2024). "Maternal intrauterine infection associated with increased levels of pro-inflammatory cytokines (IL-6, TNF-α, IL-1β) is the most important cause of preterm birth and neonatal neurological disorders." (PMID 35155393, 2022). "Pretreatment with oxt reduces TNFα by reducing NF-κB or other mechanisms, which are associated with improved neurological disorders and spatial memory." (PMID 33643574, 2021). "Induction of TNF-α in astrocytes and microglia is known to be involved in various neurological disorders associated with inflammation." (PMID 33972601, 2021). "Microglia expressing iNOS are found in many neurological diseases, and multiple stimuli such as LPS, IL-1β, TNF-α, and IFN-γ can cause the expression of iNOS, which synthesizes NO to directly damage neuronal cells." (PMID 34122094, 2021). "On the other hand, in pathological conditions, TNF is involved in the neuroinflammatory responses associated with various neurological disorders through de novo production of TNF by activated astrocytes and microglia." (PMID 34877406, 2021). "In pathological conditions, microglia produce large amounts of TNFα that serves as an important component of neuroinflammatory response that is associated with several neurological disorders including AD." (PMID 31198491, 2019). "The diseases associated with TNF were inferred using the toxicogenomics analyses of CTD, which yielded 570 nervous system diseases associated with TNF." (PMID 30700814, 2019). "The over-production of IL-1β, IL-6, and TNF-α cytokines is a hallmark of neurological diseases in the brain." (PMID 31835609, 2019). "Although TNF-inhibitors are successfully used for treating several diseases, total inhibition of TNF can cause side effects, particularly in neurological diseases." (PMID 30778285, 2019). "As one of the most interesting M1 microglial polarization markers, TNF-α has been confirmed to be implicated in the pathology of neurological disorders." (PMID 30687017, 2018). "The neurologic disease has been associated with high proviral load and increased levels of proinflammatory cytokines including IL-1, IL-6, TNF-α, and IFN-γ." (PMID 26904697, 2016). "Elevations in TNF-α, usually produced by astrocytes and microglia, are associated with several neurological disorders, and results in an inhibitory effect on glutamate transporters, resulting in increased glutamate concentration in the CNS." (PMID 25592846, 2015). "In pathological conditions, astrocytes and mainly microglia release large amounts of TNF-α; this de novo production of this cytokine is an important component of the so-called neuroinflammatory response that is associated with several neurological disorders." (PMID 24966471, 2014). "Cytokines such as tumour necrosis factor-α (TNF-α) for example, have been strongly linked to neurological disorders, whilst several studies have confirmed the ability of TNF-α to increase the permeability of brain microvascular endothelial cells." (PMID 24992685, 2014). "Wnt5a was also involved in Human Immunodeficiency Virus (HIV) associated neurological disorders by promoting IL-1β, IL-6 and TNF-α production in the spinal cord." (PMID 24993819, 2014). "BBB disruption is a common pathological feature of various neurological diseases, and inflammatory cytokines such as IL-1β and TNF-α have been considered as causative factors that damage BBB integrity by downregulating TJ proteins in BBB endothelial cells." (PMID 25535736, 2014).
neurological diseases (continued). "Additionally, the ERS-related proteins were downregulated following anti-TNF-α and anti-IL-1β treatment, including those implicated in neurological disorders such as HYOU1, PDIA4, and PDIA3." (PMID 40338234, 2025). "TNF- α, a proinflammatory cytokine, is associated with several neurological disorders." (PMID 35264055, 2022). "Moreover TNF-α is a proinflammatory mediator involved in generating an innate immune response associated with various neurological disorders." (PMID 36060699, 2022). "Interventions, including corticosteroids, melatonin, erythropoietin, anti-TNF-α antibodies, and IL-1rα administration, in clinical use for other diseases, may be also utilized for the control of neurological disorders in susceptible neonates." (PMID 32047730, 2020). "In addition to these neurological disorders, CD patients treated with anti-TNF drugs reported fatigue which was significantly associated with the use of these drugs." (PMID 29751683, 2018). "Furthermore, exacerbation of GFAP or astrogliosis along with secretion of pro-inflammatory cytokines, including TNF-α, are known to be highly expressed in the central nervous system during neurologic diseases associated with inflammation." (PMID 29262526, 2017). "If we further confirm our findings on a relatively large sample size at the BBC, we may be able to evaluate the use of cord blood TNFα methylation patterns as biomarkers for the susceptibility of immunological and neurological diseases." (PMID 26406892, 2015). "In fact, several neurological diseases are associated with increased TNFα-expression levels." (PMID 24385951, 2013). "Thus, patients who already are at increased risk (due to a genetic predisposition) of developing immune-mediated demyelination, may be at increased risk of developing neurological diseases after the introduction of anti-TNF." (PMID 24938855, 2014). "As a key mediator in both inflammatory and neuromodulatory pathways, TNF-α has been considered a potential pharmacological target for various neurological disorders." (PMID 41328216, 2025). "COX-2, increased IL-10 and TGF-β1 in the brain tissue of rats and reduced plasma cytokines TNF-α, IL-1β, IL-2, IL-3, IL-4, IL-5, IL-6, etc. and exotoxin activity in plasma of different neurological disorders." (PMID 40297338, 2025). "Faecalibacterium, a Gram-positive bacterium with potent anti-inflammatory properties, has been shown to suppress TNF-α expression and alleviate inflammation in various immunological and neurological diseases." (PMID 39981228, 2025). "NAC has been reported to suppress myotube atrophy in C2C12 cells via the TNF signaling pathway, which is closely related to the TGFβ pathway, and it has also been reported to have potential in the treatment of neurological diseases." (PMID 40474744, 2025). "Here, we present the case of a patient with diagnosed AS who, after 8 years of various specific treatments, including TNF-α inhibitors, developed muscle weakness as well as other symptoms suspicious for neurological disorders." (PMID 39459490, 2024). "When symptoms related to neurological disease were identified, anti-TNF treatment was stopped, patients had appropriate MRI/steroid management, and immune suppressive medications were changed to alternative long-term medications." (PMID 39078559, 2024). "In these neurological disorders, pro-inflammatory markers such as TNF-α, IL-1β, IL-2, INFγ, NOS, and ROS are increased according to postmortem brain samples." (PMID 38516464, 2024). "TNF-α is a pro-inflammatory cytokine and the accumulation of NF-κB has deleterious effects on neurological diseases." (PMID 37676390, 2024). "The increased mRNA expression of TNF-α at the site of neuronal damage suggests its potential as a therapeutic target for addressing this neurological disorder." (PMID 39642134, 2024). "Production of TNF, IL-6, and NO by microglia contributes to neurodegeneration and inflammation in these neurological diseases." (PMID 39000243, 2024).
neurological diseases (continued). "Recent studies indicated that activated microglia can convert astrocytes into the neurotoxic A1 phenotype via the secretion of IL‐1α, TNF‐α, and C1q, and dysfunction of astrocytes critically impacts neuronal survival in various neurological diseases." (PMID 37830170, 2023). "Among the most implicated cytokines/chemokines in both neurological disorders and IBD are tumor necrosis factor-α (TNF-α), IL-1β, IL-6, CXCL10, and CCL2." (PMID 36698151, 2023). "On the contrary, neurological presentations were inversely associated with markers of disease severity such as IL-6, TNF-α, IL-10/CXCL10, CRP, D-dimer, and LDH, all of which were significantly lower in patients with neurological diseases." (PMID 36851766, 2023). "The pro-inflammatory cytokines tumor necrosis factor alpha (TNFα) and interleukin-1beta (IL-1β) play a crucial role in the homeostasis of the central nervous system (CNS), a number of neurological diseases, and CNS injury and repair." (PMID 35625761, 2022). "AACT promotes the secretion of cytokines, including IL-6 and tumor necrosis factor-alpha (TNF-α), by regulating the NF-κB signaling pathway to be involved in nervous system diseases." (PMID 35439996, 2022). "Specifically, 2-DG reduced the expression of the inflammatory genes C3, TNFα, LCN2, and IL6, all of which are implicated in various neurodegenerative and neurological diseases." (PMID 35326266, 2022). "During CM Plasmodium parasites sequestered in the CNS within erythrocytes cause the production of proinflammatory cytokines, such as TNF-α, LTα, IFN-γ, IL-1α, and IL-1β, which contribute to the hyperinflammatory state of this neurological disorder." (PMID 35222377, 2022). "During neurological diseases or injuries, microglia-induced TNFα interacts with TNFR-1 disrupts TJs and leads to BMECs necroptosis, thereby allowing entry of toxins and pathogens into CNS." (PMID 36353359, 2022). "Another pro-inflammatory cytokine is TNFα known to interact with IL6 and is associated with neuro-inflammatory response that is linked with several neurological disorders." (PMID 33627134, 2021). "An excess of TNF‐α is an important component of the neuroinflammation response related to some neurological disorders." (PMID 34531993, 2021). "Stem cell therapies for nervous system disorders have revealed promising results on targeting and downregulating the proinflammatory factors such as IL-1β, TNF-α, and IFN-γ." (PMID 34671255, 2021). "The proportion between IL-22 and TNF serum levels was also able to discriminate neurological disease (9.2 vs 3.0, P = 0.025) from non-neurological disease during acute phase." (PMID 33776990, 2021). "In this context IMiDs, with their ability to effectively decrease TNF-α and, in general, proinflammatory cytokines levels provide a promising alternative option for the treatment of neurological disorders." (PMID 33854417, 2021). "Various neuroinflammatory and neurological diseases are characterized by a relative increase in M1 microglia-related factors such as TNF-α and IL-1β." (PMID 34604212, 2021). "TNF-α is produced by stimulated astrocytes and microglia and serves as a strong etiologic factor in many neurological disorders." (PMID 32230861, 2020). "TNF-α, being a key target that can modulate the pathology of multiple neurological disorders, has gathered enormous attention in the recent past." (PMID 31991572, 2020). "Astrocytes and neurons can also express TNF-α receptors and secrete TNF-α, which can trigger inflammatory cascades following neurological disorders." (PMID 31991572, 2020). "EA can effectively reduce the levels of interleukin-1β (IL-1β), interleukin-6 (IL-6), interleukin-18 (IL-18), and tumor necrosis factor-α (TNF-α), helping to inhibit the inflammatory response in a variety of neurological diseases." (PMID 33204250, 2020).